CAT (catalase)
Diseases named in the same sentence as CAT in open-access papers (continued):
Sharing a sentence is not in itself a finding about the gene and the disease.
vitiligo (continued). "In this study, decreased serum CAT and SOD activity as well as TAC were found in patients with NSV, indicating an impairment of antioxidative capacity in vitiligo." (PMID 34977005, 2021). "Effects of SOD, CAT, GST, MDA, IMA, age, and sex on oxidative stress in patients with vitiligo in the multivariate analysis." (PMID 30762322, 2019). "A possible explanation for this phenomenon resides in the low levels of antioxidants, including catalase (CAT), glutathione peroxidase (GPx), glucose-6-phosphate dehydrogenase (G6PD) and superoxide dismutase (SOD), in skin lesions and serum of patients with vitiligo." (PMID 40303919, 2025). "Catalase mRNA levels in cultured melanocytes from the lesional or non-lesional epidermis showed no significant changes in either the patients with vitiligo or the healthy controls." (PMID 37109666, 2023). "Taken together, an effective treatment to limit vitiligo progression and recurrence needs to improve i) the EAS enzymes (i.e., GPx, TrxR, and CAT); ii) the function and quality of mitochondria structure in melanocytes and CD8+ T cells; and iii) change the profile of the immune system." (PMID 35360245, 2022). "Low levels of catalase (CAT), glutathione peroxidase (GPx), glucose-6-phosphate dehydrogenase (G6PD), and superoxide dismutase (SOD) have been demonstrated in the epidermis and blood of vitiligo patients." (PMID 36439174, 2022). "Moreover, vitiligo patients have elevated concentrations of AOPPs and AGEs and epidermal H2O2, and decreased levels of catalase (CAT)." (PMID 34356320, 2021). "Convincing evidence indicates that, in vitiligo skin, there are high levels of epidermal H2O2 and low catalase levels, which could be increased by PC-KUS." (PMID 34356320, 2021). "High amounts of native catalase are present in the healthy skin organ but not in situations where wound healing is impaired by the lack of catalase including skin diseases, such as vitiligo, psoriasis, and presumably also in refractory leg ulcers." (PMID 32604944, 2020). "Moreover, KBL was found to modulate vitiligo via the regulation of activity of multiple series enzymes such as tyrosinase (TYR), oxidoreductase (GSTP1, CAT, MPO, and GSTM1), and controlling signal transducer (NFE2L2)." (PMID 31781265, 2019). "Since PAPLAL possesses catalase activity, it might also be useful as a treatment for H2O2-related skin diseases, including vitiligo." (PMID 25333617, 2014). "Among these strategies, NB-UVB phototherapy, widely used in vitiligo, has demonstrated not only immunomodulatory but also antioxidant effects, by reducing ROS production, enhancing activity of protective enzymes, including SOD and CAT, and downregulating proinflammatory cytokine release." (PMID 41157208, 2025). "In melanocytes isolated from vitiligo patients we observed chronic activation of Nrf2, manganese superoxide dismutase 2 (SOD2), hemeoxigenase-1 (HO-1), NAD(P)H deydrogenase quinone-1 (NQO1) and catalase genes expression that indicated a compromised redox homeostasis." (PMID 23555779, 2013). "Even in non-lesional vitiligo skin, elevated SOD, glutathione peroxidase (GPx), and deregulated catalase have been documented." (PMID 38136202, 2023). "Because there is no significant change in CAT and SOD activity between the patients receiving treatment or without treatment, we might be able to consider the therapy to increase the activity of antioxidant enzymes in vitiligo treatment." (PMID 34977005, 2021).
asthma (50 papers, 2009 to 2026). "Specifically, the GSTP1 rs1695 G allele conferred increased asthma risk, whereas the CAT rs769217 T allele exhibited protective effects." (PMID 40433469, 2025). "The combination of GSTP1 gene rs1695 and CAT gene rs7943316 constitutes the optimal model for predicting the risk of childhood asthma in the Fuzhou region." (PMID 40433469, 2025). "Tyrosine nitration and chlorination from eosinophil and neutrophil activation cause inhibition of MnSOD activity and catalase, impairing antioxidant defenses in asthma." (PMID 36421423, 2022). "In particular, we confirmed a potential role in the pathogenesis of asthma for CYBA and CAT genes that was associated with asthma in Czech and Canadian populations, respectively." (PMID 24895604, 2014). "CAT gene previously associated with urban environments and air pollution was associated with asthma after correction in our sample." (PMID 23066387, 2012). "Haplotype ATT composed of rs7943316, rs1049982, and rs769217 in the CAT gene may potentially represent a protective haplotype for the risk of childhood asthma." (PMID 40433469, 2025). "Oxidative stress is the main feature of asthma, and genetic variants in the key oxidative defense gene-CAT may have the potential to regulate the risk of new-onset asthma." (PMID 36393974, 2022). "The haplotype block 2 of the CAT gene is also associated with asthma in this sample." (PMID 23066387, 2012). "Our results show an association between CAT rs11032703 and asthma in the SLSJ sample and show that the minor allele might be a risk factor for the disease phenotype." (PMID 23066387, 2012). "This study showed an association for the CAT gene and asthma in the whole sample of the SLSJ study." (PMID 23066387, 2012). "In addition, these five gene have also been associated with the occurrence of asthma in different exposure settings and oxidative stress-related genetic variants of CAT, SOD2 and MPO have been reported to modify the association of urine phthalate metabolites levels and pulmonary function." (PMID 28208751, 2017). "Epidemiological studies have found that a functional single nucleotide polymorphism in the promoter region of CAT, G-330A that results in higher blood CAT levels, is associated with lower risk of respiratory-related school absences in children and a decreased risk of developing asthma." (PMID 23902943, 2013). "Asthma disease often exhibits diminished antioxidant capacity, with minor levels of catalase (CAT), superoxide dismutase (SOD), and glutathione." (PMID 41523289, 2026). "In patients with severe asthma, bronchial epithelial cells exhibit diminished catalase (CAT) activity, which correlates with elevated systemic markers of lipid peroxidation." (PMID 41573584, 2025). "This study identified significant associations between childhood asthma susceptibility and multiple SNPs in key antioxidant genes (GSTP1, HMOX1, and CAT), suggesting their potential utility as predictive biomarkers." (PMID 40433469, 2025). "Binary logistic regression analysis of associations between SNPs of GSTP1, HMOX1, CAT, EPHX1 gene and asthma." (PMID 40433469, 2025). "The age-stratified analysis showed that the asthma risk effects of GSTP1 rs1695, rs4891, CAT rs7943316, and HMOX1 rs17878790 were more significant in the >6-year-old group." (PMID 40433469, 2025). "Among the top 25 keywords of all four time periods, ROS, COPD, asthma, lung injury, cancer, biomarker, smoke, inflammation, apoptosis, caspase, catalase, glutathione, MDA, SOD, and TNF-alpha appeared during at least three periods." (PMID 37305540, 2023). "Downregulation of key antioxidant enzymes (SOD, CAT) and the molecule GSH is implicated in the exacerbation of inflammatory response, which occurs in steroid-resistant asthma." (PMID 36060927, 2022). "Decreases in CAT activity possibly augment oxidative stress in the airways in asthma and perpetuate the inflammatory processes." (PMID 34804178, 2021).
asthma (continued). "At week 8, CAT showed a significant difference between the asthma group and asthma AA-received group and it was decreased in the asthma AA-received group (60.67 ± 4.92 and 37.67 ± 3.68 μmol H2O2/min/mg protein, respectively) (p < 0.05)." (PMID 33162970, 2020). "After 8 weeks, SOD and CAT levels were decreased significantly in the asthma AA-received group when compared with the asthma group." (PMID 33162970, 2020). "RNASE2 and catalase (CAT) are highly expressed in eosinophils and are predictive biomarkers of atopy and asthma, respectively." (PMID 25643280, 2015). "Two haplotypes located in two genes (CAT and NQO1) were associated to asthma before correction when the sample was stratified according to proximity to aluminium industries." (PMID 23066387, 2012). "The expression, activity and/or concentration of different antioxidant measures such as SOD, GPx, CAT, vit E, and vit C have been reported to be decreased in patients with asthma or COPD." (PMID 23008817, 2012). "For example, the two associated genes (CAT and NQO1) have been associated with asthma and tobacco smoke exposures." (PMID 23066387, 2012). "The activities of superoxide dismutase and catalase in group 2 (asthma-induced) decreased significantly in the lung homogenate up to 71% (P = 0.001) and up to 77% (P = 0.004) respectively, as compared with the controls." (PMID 22654599, 2012). "Two genes were associated with asthma in the entire sample before correction (CAT and NQO1) and one was associated after correction for multiple analyses (CAT)." (PMID 23066387, 2012). "Age-stratified analysis of associations between SNPs of GSTP1, HMOX1, CAT, EPHX1 gene and asthma." (PMID 40433469, 2025). "In particular, studies on the expression of direct antioxidant responsive element (ARE)-bearing antioxidants such as glutathione, superoxide dismutase, glutathione S-transferase, and catalase have been well reported in animal asthma mice models and clinical trials." (PMID 35892624, 2022). "A recent study manifested that Divya-Swasari-Kwath, herbal decoction prescribed in India, could inhibit asthma in mice by increasing the levels of CAT, GSH, and SOD probably due to CGA that existed in herbal decoction Divya-Swasari-Kwath." (PMID 35059326, 2021). "Indeed, the antioxidant enzymes superoxide dismutases (SOD) and catalase are reduced in asthma as compared to healthy individuals, with lowest levels in those patients with the most severe asthma." (PMID 33424827, 2020). "Interestingly, a key antioxidant enzyme, catalase (CAT), was also previously associated with comorbid asthma and hypertension." (PMID 31705029, 2019). "Treatment with P.oleracea significantly reduced total WBC, neutrophil, eosinophil, monocyte, NO2, and NO3, MDA, interstitial fibrosis, emphysema, interstitial inflammation and epithelial damage, but increased lymphocyte, SOD, CAT and thiol levels compared to asthma group (p < 0.05 to p < 0.001)." (PMID 32184860, 2019). "Catalase may play a role on the oxidant-antioxidant imbalance in asthma because studies have shown a higher activity of the enzyme in affected people." (PMID 23066387, 2012). "CAT gene SNP rs769217 C>T may be a protective factor against childhood asthma in the same region." (PMID 40433469, 2025). "Antioxidant enzyme defense systems (including SOD, CAT, GPx, reduced glutathione and heme oxygenase 1) are directly regulated by Nrf2, which becomes a potential therapeutic target in lung diseases such as Idiopathic Pulmonary Fibrosis, asthma, COPD and acute respiratory distress syndrome." (PMID 36421423, 2022). "In addition, the disordered antioxidant system, including SOD and CAT, in asthma was enhanced upon rhynchophylline treatment, indicating that rhynchophylline may also improve the disordered oxidative stress in asthma." (PMID 33413331, 2021). "Previous studies have demonstrated that genes involved in oxidative stress response, including GSTP1, CAT, HMOX1, and EPHX1, participate in the pathogenesis of asthma." (PMID 40433469, 2025).
asthma (continued). "Clinical data indicate reduced expression of peroxisomal markers such as catalase (CAT) in lung tissues of asthma patients, underscoring the pathophysiological relevance of LD-peroxisome crosstalk in asthma-related ferroptosis." (PMID 41573584, 2025). "On the other hand, in the lungs of asthma patients, lower levels of antioxidant enzymes have been found (e.g., SOD, CAT and GPx)." (PMID 41154690, 2025). "The efficacy of antioxidant enzymes in asthma treatment has been also investigated, and a study of liposome-encapsulated SOD and CAT generated promising results." (PMID 39703514, 2024). "Results demonstrated that tectochrysin could enhance the activity of CAT and GPx in lung tissue, encourage the breakdown of peroxides, and shield shrimp tropomyosin-induced asthma mice from oxidative damage after tectochrysin was given intraperitoneally to a mouse asthma model for 6 days." (PMID 39759448, 2024). "In our study, DNP-HSA stimulation decreased the gene expression of SOD2 and CAT in RBL-2H3 cells, consistent with similar findings reported in patients with asthma." (PMID 38790633, 2024). "The ovalbumin-induced asthma model has been shown to result in elevated levels of MDA, a known oxidant factor, along with lowered levels of GSH, SOD, and catalase, which are all important antioxidant factors." (PMID 39295946, 2024). "In asthma patients, lower levels of SOD, CAT and GPx activity were observed in BAL fluids and respiratory epithelial cells." (PMID 39703514, 2024). "We also detected levels of oxidative stress markers (MDA, CAT and SOD), and frequent inflammation cytokines (IL-4, IL-5 and IFN-γ) in IL-13-induced BEAS-2B cells and BALF fluid of asthma mice." (PMID 36788676, 2023). "Previous studies demonstrated that GSH, CAT, and SOD have anti-oxidative stress effects, reducing lung damage in patients with asthma." (PMID 35682783, 2022). "In mice with OVA-induced asthma, the lung levels of ROS, MDA increased and the lung levels of T-AOC, SOD, CAT and GSH-Px decreased." (PMID 35210449, 2022). "SOD, CAT, and GSH are common antioxidant enzymes that can reduce lung cell damage and fibrosis in the lungs of patients with COPD or asthma." (PMID 34070405, 2021). "Catalase action was decreased in BALF from asthmatics, and SOD had lower activity in BALF and airway epithelial cells from both human and murine models of asthma." (PMID 34209324, 2021). "Meanwhile, the production of reactive oxygen species (ROS), catalase (CAT), glutathione peroxidase (GSH-Px), superoxide dismutase (SOD), nitric oxide (NO), and malondialdehyde (MDA) imbalanced in an asthma model compared with a normal model." (PMID 34258300, 2021). "Whereas, upon treatment with Rhy, the activities of SOD and CAT were increased significantly compared with the OVA group, indicating that Rhy also ameliorated the oxidative stress status of asthma." (PMID 33413331, 2021). "YFP ameliorated the level of oxidative stress in the lung of the mouse asthma model by inhibiting MDA and promoting the protein level of GSH-PX, SOD, CAT, and oxidative-related genes." (PMID 33542675, 2021). "We investigated oxidative stress in severe asthma subjects by analysing urinary 8-iso-PGF2α and the mRNA-expression of the main pro-oxidant (NOX2; NOSs) and anti-oxidant (SODs; CAT; GPX1) enzymes in the airways of SAs/ex and SAn." (PMID 30240401, 2018). "RNASE2 and catalase (CAT) are highly expressed in eosinophils and have been shown to be predictive biomarkers for atopy and asthma, respectively." (PMID 25643280, 2015). "Furthermore, the effects of Z. multiflora on CAT and MDA levels in patients with asthma remained significant, with a decrease in heterogeneity following subgroup analysis." (PMID 40330764, 2025). "In addition, the level of oxidative stress in asthma was also assessed by the activities of SOD and CAT." (PMID 33413331, 2021).
asthma (continued). "Our results indicated the preventive effect of the extract of P. oleracea on total and differential WBC counts, levels of NO2, NO3, MDA, SOD, CAT and thiol in BALF and lung pathological insults in asthmatic rats which introduce this herb as a prophylactic remedy against asthma." (PMID 32184860, 2019). "In animal models, the decreased activity of SOD and CAT in the lungs of animals injected and inhaled with OVA supported the hypothesis that asthma was related to the reduction of antioxidative capacity." (PMID 29568538, 2018). "However, some evidences relating to expression of SODs, CAT and GPX1 enzymes in relation to asthma or cigarette smoke were found in the literature." (PMID 30240401, 2018). "Interactions of maternal oxidative stress genes (GSTM1, GSTP1, CAT, and MPO) with maternal prenatal exposure to air pollutants or tobacco smoke may contribute to asthma or allergic airway responsiveness." (PMID 22272211, 2012). "Next, we wished to investigate potential molecular mechanisms whereby asthma-diseased SAEC may exhibit the altered cAMP signaling that we observe in diseased versus healthy SAEC and to also probe the expression of H2O2-generating SOD isotypes and H2O2-degrading catalase." (PMID 37865997, 2023). "The decrease of the activity of key antioxidant enzymes in the lung such as SOD, CAT and GP, as well as the level of the non-protein sulfhydryl groups in animals injected and inhaled with OVA supports allegations that ovalbumin can provoke asthma, an oxidative stress-associated disease." (PMID 22654599, 2012). "Genetic model distributions of HMOX1 gene rs2071747, CAT gene rs1049982, EPHX1 gene rs41266231, rs1051740, rs2234922 did not significantly differ between the asthma group and the control group." (PMID 40433469, 2025).